AQP1 (aquaporin 1 (Colton blood group))
Diseases named in the same sentence as AQP1 in open-access papers (continued):
Sharing a sentence is not in itself a finding about the gene and the disease.
Hydrocele testis (2 papers, 2014 to 2023). Accumulation of clear fluid in the between the layers of membrane (tunica vaginalis) surrounding the testis. "Epigenetics such as DNA methylation and single nucleotide polymorphism in the AQP1 gene may be involved in the pathogenesis of adult-onset hydrocele testis." (PMID 24817884, 2014). "The development of hydrocele testis involves not only an increase in fluid influx due to an increase in AQP1 protein but also a factor of decreased fluid absorption due to changes in the lymphatic vessels of the tunica vaginalis." (PMID 38021552, 2023). "This hypomethylation may contribute to enhanced AQP1 protein expression in the tunica vaginalis of patients with hydrocele testis and the development of hydrocele testis." (PMID 38021552, 2023). "The scatter diagram showing the densities of AQP1-expressing capillaries and lymphatic vessels could not be used to differentiate between patients with hydrocele testis and the controls." (PMID 24817884, 2014).
idiopathic pulmonary fibrosis (2 papers, 2018 to 2021). Idiopathic pulmonary fibrosis (IPF) is a nonneoplastic pulmonary disease that is characterized by the formation of scar tissue within the lungs in the absence of any known cause. "It has been reported that expression of AQP1 is absent in healthy alveolar epithelium, but is observed in biopsies from patients with idiopathic pulmonary fibrosis." (PMID 34570783, 2021).
interstitial lung disease (2 papers, 2011 to 2018). A diverse group of lung diseases that affect the lung parenchyma. "In the present study we analyzed expression of AQP1 in lung biopsies of patients diagnosed with IPF, and compare it to biopsies derived from diverse interstitial lung diseases such as others pneumonias, hypersensitivity pneumonitis, sarcoidosis, or normal lungs." (PMID 29774214, 2018).
lupus (2 papers, 2022 to 2025). "The authors reported an increase in AQP1 expression in lupus glomeruli and a decrease in AQP1, AQP2, and AQP3 expression in renal tubules based on immunohistochemistry (IHC)." (PMID 40072108, 2025). "A low AQP1 level was linked to oocyte meiosis, cell cycle, base excision repair, and ubiquitin-mediated proteolysis, and its high level was linked to VEGF signaling pathway, PPAR signaling pathway, complement and coagulation cascades, and systemic lupus erythematosus." (PMID 36059959, 2022).
lupus nephritis (2 papers, 2025). Glomerulonephritis in the context of systemic lupus erythematosus. "We observed that VIM (vimentin) and AQP1 (aquaporin-1) were consistently significant across all three conditions, with meta-p values of 9.03e-141, 0, and 1.14e-121 for VIM, and 0, 1.79e-193, and 8.43e-14 for AQP1 in lupus nephritis, CKD, and control samples, respectively." (PMID 39974940, 2025).
malignant glioma (2 papers, 2015 to 2023). A grade III or grade IV glioma arising from the central nervous system. "A characteristic common to malignant gliomas is the occurrence of brain edema, which has been linked to the functioning of Aquaporin 1 (AQP1)." (PMID 38057925, 2023). "Of these, AQP1 and AQP4 proteins are found highly expressed in the most malignant gliomas." (PMID 26083629, 2015).
ocular hypertension (2 papers, 2024 to 2025). Abnormally high intraocular pressure. "The present study demonstrates that simultaneous knockdown of AQP1 and CA2 in the ciliary body lowers IOP in wild-type mice and a steroid-induced ocular hypertension mouse model." (PMID 40575705, 2025). "AAV-Cas13d-mediated AQP1 and CA2 knockdown was tested in a dexamethasone-induced ocular hypertension model." (PMID 40575705, 2025).
oncocytoma (2 papers, 2014 to 2022). "Western blot analysis yielded a band of 28 kD molecular weight for all eleven fresh urine samples from individuals with RCC and a single patient with oncocytoma, indicating the presence of AQP1 protein." (PMID 24803718, 2014).
Peritoneal Fibrosis (2 papers, 2018 to 2022). Disorder characterized by a wide range of structural changes in PERITONEUM, resulting from fibrogenic or inflammatory processes. "Despite accumulating, evidence indicating the importance of AQP1 upon PD, changes in AQP1 during the progression of peritoneal fibrosis remain unclear." (PMID 35453560, 2022). "As abnormal expression of AQP-1 and ZO-1 leads to degenerated function of the peritoneum, and abnormal expression of PPAR-γ is related to peritoneal fibrosis and neoangiogenesis, we determined the effect of rosiglitazone on the expression of AQP–1, ZO-1, and PPAR-γ." (PMID 29871973, 2018).
polycystic kidney disease (2 papers, 2020 to 2022). A usually autosomal dominant and less frequently autosomal recessive genetic disorder characterized by the presence of numerous cysts in the kidneys leading to end-stage renal failure. "Previous studies have shown that AQP1 is involved in other pathophysiological mechanisms such as tumor development, inflammatory cytokine release (via the NF-κB pathway), and polycystic kidney disease (via the Wnt pathway)." (PMID 36012630, 2022). "In previous studies, AQP1 was demonstrated to be involved in other pathophysiologic mechanisms, such as tumor development, inflammatory cytokines release (via NF-Κb signaling pathway), and polycystic kidney disease (via Wnt signaling pathway)." (PMID 33396834, 2020).
Priapism (2 papers, 2023 to 2024). A painful and harmful medical condition in which the erect penis doesn't return to its flaccid state, despite the absence of both physical and psychological stimulation, within four hours. "SNPs of AQP1 and other genes were found to have an association in male patients with a history of priapism indicating AQP1’s involvement in important cellular processes such as cell adhesion and cell signaling." (PMID 36913438, 2023).
primary biliary cirrhosis (2 papers, 2024). "AQP1 was primarily found in the proliferating arterial capillaries in human cirrhotic and late-stage primary biliary cirrhosis (PBC) livers, suggesting that AQP1 may trigger angiogenic responses." (PMID 39596202, 2024).
sarcoidosis (2 papers, 2018 to 2020). Sarcoidosis is a multisystemic disorder of unknown cause characterized by the formation of immune granulomas in involved organs. "Even in cases of intense inflammatory activity like hypersensitivity pneumonitis or sarcoidosis, there is not expression of AQP1 in alveolar epithelial cells." (PMID 29774214, 2018). "Here we analyzed expression of AQP1 in lung biopsies of patients diagnosed with IPF, and compared it to biopsies derived from patients with diverse lung pneumonies, such as hypersensitivity pneumonitis, sarcoidosis or normal lungs." (PMID 29774214, 2018).
sudden infant death syndrome (2 papers, 2021 to 2023). Unexpected death in infancy which remains unexplained following autopsy, review of the medical history, and investigation of the death circumstances and death scene. "Moreover, the major allele of rs17159702, located in the intron 1 of the AQP1 gene, was previously associated with sudden infant death syndrome." (PMID 38021552, 2023).
uremia (2 papers, 2020 to 2026). A clinical syndrome associated with the retention of renal waste products or uremic toxins in the blood. "Further studies in uremia-specific animal models and clinical cohorts will be essential to clarify the pathophysiological and therapeutic significance of AQP1 in this condition." (PMID 42322089, 2026). "Our results confirmed these findings and showed that there are indeed differences in the levels of expression and that Aqp1 levels are significantly diminished in uremia in almost all the GP strata." (PMID 32630463, 2020).
urinary stones (2 papers, 2017 to 2023). "In our study, the risk allele of rs1000597 on AQP1 may also promote development of urolithiasis through affecting the level of serum calcium, uric acid, and urinary pH." (PMID 28361944, 2017). "Therefore, the SNPs rs12669187 and rs1000597 are likely to be associated with the regulation of FAM188B and AQP1 expression, which could affect the urine concentration and increase the risk of urolithiasis development." (PMID 28361944, 2017).
vasculitis (2 papers, 2010 to 2019). "In vasculitis and intraretinal inflammatory infiltrates, decreased AQP1 expression was observed due to the loss of photoreceptors and the characteristic radial labeling of AQP4 was lost." (PMID 20383338, 2010). "In mouse vasculitis and intraretinal inflammatory infiltrates, AQP1 protein expression downregulated TNF-α in mouse retinal pigment epithelium (RPE) cells." (PMID 31529146, 2019). "Strikingly, retinal endothelial cells did not express AQP1 in normal or EAU retina, even on vasculitis lesions." (PMID 20383338, 2010).
ZIKV infection (2 papers, 2019 to 2021). "The data of IHC indicated that AQP1 distribution in epithelial cells was changed to interstitial distribution after ZIKV infection, especially in IS." (PMID 33667230, 2021). "After ZIKV infection, the levels of AQP1 and AQP9 were significantly decreased, and the levels of other AQPs were increased at the transcriptional levels, which might result from the disruption of EEC." (PMID 33667230, 2021). "After ZIKV infection, the expression of AQP1 in epithelial cells in all segments was downregulated." (PMID 33667230, 2021). "We found that both of ZIKV infection and recombinant IL-1β treatment resulted in a significant decrease expression of AQP1 and AQP2 in primary murine renal epithelial cells thus inducing water re-absorption disorder, which indicated that inflammasome was involved in ZIKV-induced renal dysfunction." (PMID 31474993, 2019).
acute myeloid leukemia (1 paper, 2020). Acute myeloid leukemia (AML) is a group of neoplasms arising from precursor cells committed to the myeloid cell-line differentiation. "This research aims to explore the prognostic value of AQP-1 in elderly cytogenetically normal acute myeloid leukemia (CN-AML)." (PMID 32373535, 2020).
adenovirus infection (1 paper, 2021). "Expressions of AQPs were altered in the pathological conditions: AQP1 expression was decreased in the lung with acute hypoxic lung injury, while adenovirus infection decreased both AQP1 and AQP414." (PMID 34040066, 2021).
allergic rhinitis (1 paper, 2018). Inflammation of the nasal mucous membranes caused by an IgE-mediated response to external allergens. "Studies using rat models of nasal mucosa of allergic rhinitis (AR) showed that intranasal administration of β-GA downregulates AQP1 together with that of eotaxin 1 (CCL11) and eosinophil (EOS) in nasal mucosa of allergic rhinitis rats and cast effects on inhibiting the progress of AR." (PMID 29721498, 2018).
amyloid (1 paper, 2025). "Furthermore, elevated Aqp1 expression can improve cell motility and Aβ clearance at amyloid deposition sites, indicating a response to Aβ-induced stress." (PMID 41168263, 2025).
anemia (1 paper, 2025). A reduction in the number of red blood cells, the amount of hemoglobin, and/or the volume of packed red blood cells. "Additionally, AQP1 was associated with filtration in a fetal anemia model and pulmonary edema in a newborn lamb model replicating infant CPB with hypothermic circulatory arrest." (PMID 41010898, 2025). "A high amount of AQP1 in the fetal endothelial membrane may be associated with filtration in the fetal anemia model, when induced by isovolumetric hemorrhage in ewes." (PMID 41010898, 2025).
Anxiety (1 paper, 2021). Intense feelings of nervousness, tension, or panic often arise in response to interpersonal stresses. "miR-144-3p targets a number of genes including Pten, Spred1, EGFR, Nrf2, AQP1, NGF, Brg1 and Notch, which are implicated in the stress response, anxiety and mood stabilizer treatment." (PMID 34674715, 2021).
autoimmune hemolytic anemia (1 paper, 2023). Autoimmune hemolytic anemia (AIHA) is an autoimmune disorder in which various types of auto-antibodies are directed against red blood cells causing their survival to be shortened and resulting in hemolytic anemia. "AQP1 antibodies have been detected in autoimmune hemolytic anemia (AΙHA) and in Sögren’s syndrome (SS)." (PMID 37629163, 2023). "Interestingly, in Section 3.2 we describe a case with high titer of AQP1 antibodies and the development of both autoimmune hemolytic anemia (AIHA) and a clinical relapse in a patient with NMOSD phenotype; recovery of both diseases occurred with a simultaneous dramatic drop of AQP1-Abs." (PMID 37629163, 2023).
autoimmune uveitis (1 paper, 2010). An autoimmune form of uveitis (disease). "We have therefore evaluated the expression of AQP1 and AQP4 on BRB cells during experimental autoimmune uveitis (EAU) in mice." (PMID 20383338, 2010).
brain trauma (1 paper, 2019). "Taken together, these results provided direct functional evidence for the involvement of AQP1 in CSF dynamics, suggesting AQP1 deletion might be protective in a brain trauma model." (PMID 31023968, 2019).
cataract (1 paper, 2023). Partial or complete opacity of the crystalline lens of one or both eyes that decreases visual acuity and eventually results in blindness. "Various studies have shown the development of early onset bilateral cataracts in AQP0 and AQP1 knockout mice." (PMID 37511188, 2023).
colon adenocarcinoma (1 paper, 2016). "AQP1 knockout mouse models of human cancers showed marked inhibition of tumor-induced angiogenesis, and in pre-clinical studies of colon adenocarcinomas, forced over-expression of AQP1 was shown to increase angiogenesis, invasion and metastasis." (PMID 26912239, 2016).
colorectal adenocarcinoma (1 paper, 2019). The most common type of colorectal carcinoma. "In two colorectal adenocarcinoma cell lines, high levels of AQP1 transcript were confirmed in HT29, and low levels in SW480 cells, by quantitative PCR (polymerase chain reaction)." (PMID 31477744, 2019). "The two human colorectal adenocarcinomas cell lines with epithelial morphologies selected for comparison were: HT29 with high levels of AQP1 expression, and SW480 with low levels of AQP1 expression." (PMID 31477744, 2019).
congenital hemangioma (1 paper, 2022). A hemangioma present and fully formed at birth. "In contrast to congenital hemangiomas, IHs expressed GLUT-1 and AQP1 in their EC and TC, respectively." (PMID 35563552, 2022).
congenital hydrocephalus (1 paper, 2022). Hydrocephalus that is present at birth. "In Texas rats with congenital hydrocephalus, choroidal AQP1 expression was reduced early in life but normalized on postnatal day 26, just before death." (PMID 36293145, 2022).
congenital hydronephrosis (1 paper, 2021). Congenital hydronephrosis is a renal urinary disease characterized by distension and dilation of the renal pelvis and calyces secondary to various congenital obstructive malformations of the kidneys and urinary tract that can evolve to renal atrophy. "Although no study on the relationship between human renal and uEV‐AQPs has been reported, the decrease in the renal expression of AQP1 in patients with pediatric congenital hydronephrosis has been shown to be dependent on the degree of renal dysfunction." (PMID 34435473, 2021).
Constipation (1 paper, 2025). Infrequent or difficult evacuation of feces. "In human, the expressions of AQP3 and AQP8 were upregulated in patients with constipation, whereas the expressions of AQP1, AQP7, and others were downregulated." (PMID 40807605, 2025).
corneal dystrophies (1 paper, 2013). "If loss of SLC4A11-mediated water-flux causes corneal dystrophies, then loss of AQP1 might cause the same phenotype as loss of SLC4A11." (PMID 23813972, 2013).
corneal edema (1 paper, 2010). "While it is unclear if down regulation of AQP1 is directly related to corneal endothelial disease, it is suggested that increased AQP1 expression may reduce corneal edema." (PMID 20806077, 2010).
cystinosis (1 paper, 2025). Cystinosis is a metabolic disease characterized by an accumulation of cystine inside the lysosomes, causing damage in different organs and tissues, particularly in the kidneys and eyes. "Additionally, we observed differentially methylated cytosines in Cubilin (Cubn) and Aquaporin 1 (Aqp1), genes critical for kidney epithelial cell function, both of which are significantly downregulated in cystinosis." (PMID 40917744, 2025). "Notably, the effect was more pronounced for CUBN and AQP1 in cystinotic cells, suggesting that DNA methylation plays a key role in repressing these transporters in cystinosis and that demethylating agents may help restore their expression." (PMID 40917744, 2025).
demyelination (1 paper, 2023). "The present review focuses on the reliable detection of AQP1-Abs by a panel of different methods and on the possible relevance of these antibodies with CNS astrocytopathy and associated demyelination." (PMID 37629163, 2023).
depression (1 paper, 2022). "For AQP1 and ITGB4, studied only in rodent models of depression, the present study was the first to implicate them in human suicidal behavior." (PMID 35806070, 2022).
diabetic retinopathy (1 paper, 2014). "A similar upregulation of AQP1 in retinal glial cells was previously observed in experimental diabetic retinopathy and after transient retinal ischemia." (PMID 23755094, 2014).
disc degeneration (1 paper, 2015). "Together, our results demonstrate that AQP1 and AQP5 expression is sensitive to human disc degeneration and that HIF-1α uniquely maintains basal expression of both AQPs in NP cells, independent of oxemic tension and HIF-1 binding to promoter HREs." (PMID 25844601, 2015).
endolymphatic hydrops (1 paper, 2024). An accumulation of endolymph in the inner ear (labyrinth) leading to buildup of pressure and distortion of intralabyrinthine structures, such as cochlea and semicircular canals. "In guinea pigs with endolymphatic hydrops, electroacupuncture was found to be able to increase the expression level of aquaporin 1 (AQP1) while also having a benign effect on serum ion concentration." (PMID 39722819, 2024). "This suggests that the improvement of endolymphatic hydrops by electroacupuncture may be related to the up-regulation of cochlear AQP1 expression and affected by the change in ion concentration." (PMID 39722819, 2024).
enteritis (1 paper, 2016). Inflammation of the small intestine. "On the other hand, the downregulated expression of several AQPs (AQP1, AQP3, AQP4, AQP7, AQP8, AQP10 and AQP11) in the small and large intestines has been observed in the process of either enteritis or diarrhea." (PMID 27589719, 2016).
esophageal adenocarcinoma (1 paper, 2018). A malignant tumor with glandular differentiation arising predominantly from Barrett mucosa in the lower third of the esophagus. "Our data also showed that AQP1 was highly expressed in esophageal adenocarcinoma and in esophageal basaloid-type SCC." (PMID 30042826, 2018).
esophageal squamous cell carcinoma (1 paper, 2018). Esophageal squamous cell carcinoma (ESCC) is a type of esophageal carcinoma (EC) that can affect any part of the esophagus, but is usually located in the upper or middle third. "Further, our immnohistochemical analysis indicated that AQP1 was expressed in esophageal squamous cell carcinoma and affect poor prognosis." (PMID 30042826, 2018). "The objectives of the present study were to investigate the role of AQP1 in the regulation of genes involved in tumor progression and the clinicopathological significance of its expression in esophageal squamous cell carcinoma (ESCC)." (PMID 30042826, 2018).